IKBKE (inhibitor of nuclear factor kappa B kinase subunit epsilon)
Diseases named in the same sentence as IKBKE in open-access papers (continued):
Sharing a sentence is not in itself a finding about the gene and the disease.
glioma (15 papers, 2017 to 2025). A benign or malignant brain and spinal cord tumor that arises from glial cells (astrocytes, oligodendrocytes, ependymal cells). "In low-grade glioma, IKBKE regulates autophagy and contributes to disease progression through pathways such as PI3K/AKT/mTOR." (PMID 41378297, 2025). "IKBKE overexpression has been reported in glioma and NF-κB, a transcription factor well-established to increase a stem cell-phenotype, migration, radiation resistance, aerobic glycolysis, and angiogenesis in GBM." (PMID 37370851, 2023). "In this article, we first demonstrated that CYT387, as an IKBKE inhibitor, inhibited glioma cell proliferation, migration, and invasion in vitro; accelerated cell apoptosis; and arrested the cell cycle at the G2/M checkpoint." (PMID 34544426, 2021). "LATS1/2 degradation can be mediated by IKBKE (inhibitor of nuclear factor kappa-B kinase subunit epsilon), which was shown to be upregulated in glioma." (PMID 33477668, 2021). "Recent studies have also shown that IKBKE is overexpressed in glioma, ovarian cancer, prostate cancer, non-small cell lung cancer, gastric cancer and renal clear cell carcinoma." (PMID 34544426, 2021). "IKBKE knockdown in glioma cells decreased Bcl‐2 expression and promoted cleavage and activation of caspase‐3, which suggested that IKBKE induced glioma cell resistance to apoptosis." (PMID 31733040, 2020). "Silencing of IKBKE in human glioma cells using siRNA showed significant inhibition of cell growth, migration, and invasion and arrested tumor cells at the G0/G1 phase." (PMID 31733040, 2020). "The overexpression of IKBKE is closely related to the stage of the glioma, and the invasion and migration of IKBKE cells are reduced after IKBKE is silenced with synthetic siRNAs." (PMID 33194668, 2020). "Lu et al32 also demonstrated that IKBKE promoted glioma cell proliferation, migration, invasion, and EMT (epithelial‐mesenchymal transition)." (PMID 31733040, 2020). "Subsequently, Li et al31 confirmed that the overexpression of IKBKE in gliomas was positively related to the grade of glioma by ICH analysis." (PMID 31733040, 2020). "In conclusion, our study is the first to demonstrate that amlexanox displays promising anticancer activity against glioma cells harboring high levels of IKBKE in vitro and in vivo." (PMID 29048430, 2017). "Recent studies have shown that IKBKE is also overexpressed in ovarian cancer, endometrial carcinoma, prostate cancer, glioma, renal clear cell carcinoma and non-small cell lung cancer." (PMID 28548934, 2017). "IKBKE is also closely related to cancer grade in ovarian cancer, glioma, and lung squamous cell cancer." (PMID 28548934, 2017). "In conclusion, our research aimed that IKBKE can regulate glioma cell proliferation, migration, and invasion abilities in vitro and in vivo." (PMID 28548934, 2017). "In this study, we confirmed that IKBKE promoted glioma proliferation, migration and invasion in vitro." (PMID 28548934, 2017). "The experimental results demonstrated that the average number of cells with IKBKE-shRNA across chambers was decreased significantly compared to cells with scrambled group, indicating that IKBKE plays an important role in glioma cell invasion." (PMID 28548934, 2017). "As for β-catenin, vimentin and snail, fluorescence intensities of IKBKE-shRNA-transfected glioma cells were lower than those infected scrambled vector." (PMID 28548934, 2017). "In this article, we demonstrated that IKBKE is overexpressed in several glioma cell lines and can promote glioma cell proliferation, migration and invasion." (PMID 28548934, 2017). "Finally, let-7b/i decreases migration and proliferation of glioma cells by binding to IKBKE mRNA 3′ UTR to decrease IKBKE expression, which increases E-cadherin (E-cad) expression." (PMID 37370851, 2023).
glioma (continued). "Similarly, miR-98 decreases migration of glioma cells by binding to IKBKE mRNA 3′ UTR to decrease IKBKE expression, decreasing NF-κB p65 subunit nuclear translocation, which decreases expression of matrix metalloproteinase (MMP)-9." (PMID 37370851, 2023). "In addition, we verified that CYT387 increased Hippo pathway activity to inhibit glioma malignancy and that IKBKE directly interacted with YAP1 and TEAD2, as determined by using coimmunoprecipitation (co-IP)." (PMID 34544426, 2021). "Furthermore, when nude mice were treated with IKBKE siRNA in vivo, the tumor growth of established subcutaneous gliomas was significantly attenuated." (PMID 31733040, 2020). "The results suggested that amlexanox had an effect on glioma cells in vivo by downregulating IKBKE." (PMID 29048430, 2017). "In this study, we primarily confirmed that IKBKE downregulation could inhibit glioma cell abilities including proliferation, migration and invasion in vitro." (PMID 28548934, 2017). "Interestingly, YAP1 expression in the glioma cell nucleus transfected with IKBKE-shRNA was reduced much more than in the cytoplasm." (PMID 28548934, 2017). "However, it should be noted out that the effects on other IKBKE-regulated pathways may also contribute to the activity of amlexanox in glioma cells." (PMID 29048430, 2017). "Given that IKBKE knockdown could inhibit the tumourigenicity of glioma cells in vitro." (PMID 28548934, 2017). "MAPK3 and CX3CL1 were strongly positive; NFE2L2, HSP90AB1, and SUPT20H were moderately positive; and FKBP1B, BIRC5, NPC1, IKBKE, BID, and PTEN were weakly positive in glioma tissue relative to their expression levels in normal tissue." (PMID 33194668, 2020). "The result indicated the existence of combination between IKBKE and LATS1/2 in glioma cells." (PMID 29048430, 2017). "Furthermore, the authors demonstrated that IKBKE did not alter mRNA levels of LATS1/2 in glioma cells but was directly bound to LATS1/2, and facilitated its polyubiquitin degradation." (PMID 33477668, 2021). "Meanwhile, our data showed that IKBKE did not alter mRNA levels of LATS1/2 in glioma cells." (PMID 29048430, 2017).
ovarian carcinoma (14 papers, 2010 to 2025). A malignant neoplasm originating from the surface ovarian epithelium. "IKBKE overexpression is linked to chemotherapy resistance, particularly to cisplatin and paclitaxel in breast and ovarian cancers, as well as resistance to EGFR tyrosine kinase inhibitors in non-small cell lung cancer." (PMID 41378297, 2025). "Moreover, IKBKE overexpression was associated with late stage, high grade, poor prognosis, and resistance to cisplatin, all of which suggested that IKBKE was a critical mediator of ovarian cancer progression and drug resistance." (PMID 31733040, 2020). "For instance, Lee found elevated IKBKE levels in 63 of 96 ovarian cancer specimens, which correlated with advanced and high-grade tumors." (PMID 41378297, 2025). "Of the 96 ovarian cancer specimens examined, 63 had meaningful IKBKE overexpression at both the mRNA and protein levels." (PMID 31733040, 2020). "Taken together, IKBKE is a critical coordinator of progression, invasion, and metastasis in ovarian cancer." (PMID 31733040, 2020). "Hsu et al46 surveyed IKBKE expression in 42 primary ovarian carcinomas and 78 metastatic carcinomas." (PMID 31733040, 2020). "In an in vitro experiment, silencing of IKBKE slightly decreased growth and invasion in ovarian cancer cell lines." (PMID 31733040, 2020).
prostate carcinoma (12 papers, 2017 to 2026). A carcinoma that arises from epithelial cells of the prostate gland. "IKBKE (inhibitor of nuclear factor kappa-B kinase subunit epsilon) is an oncogenic kinase implicated in multiple cancers, including breast, ovarian, lung, and prostate cancer." (PMID 41378297, 2025). "We also examined the correlation between the expression of AR signature genes (AR score) and IKBKE expression levels in TCGA prostate cancer patient samples." (PMID 41542764, 2026). "IKBKE expression was elevated in the malignant cells versus normal control tissue among the 17 analyzed cancer types except prostate cancer." (PMID 41542764, 2026). "HDAC2 knockdown also abolished DHT repression of IKBKE in LNCaP cells, a different AR prostate cancer cell line." (PMID 41542764, 2026). "They observed that cytoplasmic IKBKE staining in HS tumors was higher than that in normal tissues and that cytoplasmic expression of IKBKE in CR tumor tissues was highest in all PC (prostate cancer) tissues." (PMID 31733040, 2020). "We next sought to determine whether the AR suppresses IKBKE mRNA transcription or affects its stability in prostate cancer cells." (PMID 41542764, 2026). "Notably, IKBKE has emerged as a therapeutic target for advanced prostate cancer due to its role in inhibiting resistance to androgen receptor-targeted therapies, as well as its effects on proliferation, migration, and colony formation." (PMID 41378297, 2025). "In advanced prostate cancer, IKBKE activity enhances AR levels via modulation of the Hippo pathway." (PMID 36035183, 2022). "Furthermore, they observed a significant growth delay both in vitro in IKBKE‐silenced prostate cancer cell lines and in vivo in xenografted mice, and they also observed longer survival in IKBKE knockdown xenografted mice." (PMID 31733040, 2020). "Our observations suggest that rejuvenating IKKε signaling via targeting of IKBKE eRNA in combination with radiation could be an effective means to trigger anticancer immunity in immunologically “cold” cancers such as prostate cancer." (PMID 41542764, 2026). "Therefore, it can be concluded that in prostate cancer, YAP not only regulates AR expression but also does so in an IKBKE-dependent manner." (PMID 39963114, 2025). "Peant et al53 also confirmed that IKBKE overexpression induced NF‐κB‐independent stimulation of IL‐6 expression through the activation and nuclear translocation of transcription factor C/EBP‐β in prostate cancer cells." (PMID 31733040, 2020). "Furthermore, AR positive cell lines appear more sensitive to IKBKE inhibition upon comparison of GI50 values and ‘normal’ prostate cancer cells appear to be less sensitive." (PMID 32324216, 2020). "Similarly, Seo et al51 analyzed the expression of IKBKE in 107 prostate adenocarcinoma tissues by immunohistochemistry and found that IKBKE was overexpressed in 70.1% of prostate cancers, which indicated that IKBKE might play a role in the tumorigenesis of prostate cancers." (PMID 31733040, 2020). "Meta-analysis of prostate cancer TCGA database revealed a negative correlation between HDAC2 and IKBKE mRNA expression." (PMID 41542764, 2026).
asthma (10 papers, 2015 to 2025). "IKBKE is a known target of the NFκB, a transcription factor involved in the inflammatory response of asthma pathogenesis and airway remodeling." (PMID 36835202, 2023). "Interestingly, pharmacological inhibitors of IKBKE are used in treatment of asthma, allergic rhinitis and aphthous ulcers and a potential role for these inhibitors has also been identified in obesity related metabolic disorders, lung cancer and glioblastoma." (PMID 32324216, 2020). "Moreover, IKBKE itself is a known therapeutic target for asthma, with IKBKE targeting demonstrating significant attenuation of airways responsiveness and inflammation in a murine model of asthma." (PMID 28749975, 2017). "Amlexanox, an IKBKE/TBK1 inhibitor developed to treat ulcers, allergic rhinitis and asthma, results in a G0/G1 arrest in glioblastoma cells and induction of apoptosis." (PMID 32324216, 2020). "The role of IKBKE signaling for the stiffness-induced phenotype was further tested using a pharmacological inhibitor of IKBKE, Amlexanox, a dual IKBKE/TBK1 inhibitor that is clinically used for the treatment of recurrent aphthous ulcers and asthma." (PMID 40468448, 2025).
atherosclerosis (10 papers, 2013 to 2024). A disease characterized by the build-up of fatty material and calcium deposition in the arterial wall resulting in partial or complete occlusion of the arterial lumen. "The inhibitor of κB kinase epsilon (IKBKE, IKKε, or IKKi) has been identified as an emerging modulator that limits chronic inflammation during metabolic disease and atherosclerosis." (PMID 30134788, 2018). "Furthermore, IKBKE ablation in apoE−/− mice enhances NLRP3 inflammasome priming and promotes atherosclerosis." (PMID 30134788, 2018).
cardiac hypertrophy (10 papers, 2013 to 2026). "CYTOR expression in the heart appears to be positively correlated with IKBKE expression, which has been reported to protect the heart from developing pathological cardiac hypertrophy through the IKKi and NF-κB signaling pathway." (PMID 32754048, 2020). "In both in vivo and in vitro models of Ang-II-induced cardiac hypertrophy, miR-155 is overexpressed, reducing the expression of the inhibitor of nuclear factor kappa-B kinase subunit epsilon (IKBKE), promoting activation of the nuclear factor kappa- B (NF-κB), inflammation and cardiac hypertrophy." (PMID 34944415, 2021).
glioblastoma (10 papers, 2017 to 2025). The most malignant astrocytic tumor (WHO grade IV). "This PLK4-NF-κB interaction has also been studied in glioblastoma where PLK4 was found to induce NF-κB transactivation and increased chemoresistance by phosphorylating IKK-epsilon (IKBKE) in glioblastoma cells." (PMID 40940791, 2025). "In this paper, we focused on exploring the novel mechanism by which CYT387, as a potent IKBKE inhibitor, inhibits the malignant progression of human glioblastoma." (PMID 34544426, 2021). "Of these, IKBKE (inhibitor of nuclear factor kappa-B kinase subunit epsilon) and YBX1 (Y box binding protein 1) have been previously implicated in glioblastoma pathogenesis and metabolic targeting of virotherapy." (PMID 34045642, 2021). "Yuan et al84 testified through luciferase reporter assay analysis that miR‐let‐7b/i suppressed glioblastoma cell invasion and migration by targeting IKBKE to reduce IKBKE expression." (PMID 31733040, 2020). "More importantly, we testify that IKBKE accelerates EMT of glioblastoma cells via IKBKE-dependent YAP1/TEAD2 activation." (PMID 28548934, 2017). "In this study, we demonstrated the effects of amlexanox on the migration and invasion of glioblastoma cells through the downregulation of IKBKE levels, which ultimately targets the Hippo pathway." (PMID 29048430, 2017). "These researches and our experimental data provide the theoretical basis that IKBKE promotes glioblastoma growth and EMT through IKBKE-dependent YAP1/TEAD2 activation." (PMID 28548934, 2017). "In addition, Liu et al82 certified that amlexanox, as an IKBKE inhibitor, suppresses glioblastoma cell growth and development in vivo and in vitro." (PMID 31733040, 2020). "Additionally, we respectively overexpress YAP1 and TEAD2 in glioblastoma cell lines transfected with IKBKE-shRNA." (PMID 28548934, 2017). "Silencing IKBKE can inhibit glioblastoma progression in vitro and in vivo." (PMID 28548934, 2017). "Therefore, we speculated that IKBKE may promote glioblastoma progression via regulation of the Hippo pathway." (PMID 34544426, 2021). "Liu et al82 demonstrated that direct interaction of IKBKE with LATS induced degradation of LATS, thereby inhibiting the activity of the Hippo pathway and facilitating glioblastoma cell line development." (PMID 31733040, 2020). "Zhang et al81 reported that IKBKE increased the expression of YAP1, promoted YAP1 translocation into the nucleus and decreased the expression of p‐YAP1 (Ser127), which was a degradative marker of YAP1, thereby promoting the progression of glioblastoma." (PMID 31733040, 2020). "Similarly, Zhang et al81 discovered that miR‐let‐7b/i could decrease the expression of IKBKE, while IKBKE also decreased the expression of miR‐let‐7b/i through inducing YAP1, thus forming a miR‐let‐7/IKBKE/YAP1 regulatory loop to regulate glioblastoma cell growth." (PMID 31733040, 2020).
pancreatic cancer (8 papers, 2018 to 2026). "In an in vivo experiment, knockdown of IKBKE also inhibited the initiation and progression of pancreatic tumors in mice." (PMID 31733040, 2020). "Interestingly, ectopic GLI1 expression in KRAS-expressing mice enhanced IKBKE expression and nuclear RelA staining, and the knockdown of IKBKE expression in pancreatic cancer cell lines impaired their ability to grow in soft agar and induced apoptosis by caspase 3 cleavage." (PMID 34572373, 2021). "Similarly, NFκB seems to regulate GLI expression via direct interaction with GLI promotor region, and GLI utilizes the I-kappa-B kinase epsilon (IKBKE) to increase the NFκB pathway activity and, in consequence, accelerate pancreatic tumor formation." (PMID 29695137, 2018).
breast tumors (6 papers, 2011 to 2022). "IKBKE is a gene overexpressed in approximately 30% of human breast tumors and represents an emerging link between cancer and inflammation." (PMID 31665136, 2019). "Thus, breast tumors harboring IKBKE copy-number gain studied by Boehm and coll." (PMID 28532474, 2017).
gastric cancer (6 papers, 2016 to 2020). A primary or metastatic malignant neoplasm involving the stomach. "Subsequently, Geng et al36 testified that IKBKE was overexpressed in gastric cancer by immunohistochemical staining, which was correlated with more advanced disease and poor overall survival of patients." (PMID 31733040, 2020). "Lee et al35 analyzed the expression levels of IKBKE and TBK1 using tissue microarray samples obtained from 1107 gastric cancer patients and found upregulation of IKBKE in 150 samples (13.6%) and upregulation of TBK1 in 38 samples (3.4%)." (PMID 31733040, 2020). "Silencing of IKBKE effectively suppressed the migratory and invasive capabilities of human gastric cancer cells in vitro and tumorigenicity and metastasis in vivo." (PMID 31733040, 2020). "Two types of metastatic gastric cancer tissues and gastritis tissues were randomly selected for IKBKE, NF-κB p65 and phospho-NF-κB p65 proteins analysis by immunohistochemistry." (PMID 26934326, 2016). "The percentage of positively stained cells for IKBKE, NF-κB p65 and phospho-NF-κB p65 in the diffuse type of gastric cancer were up to 83.5%, 80.8% and 65.0%, respectively, but the positive cell percentages of the latter two in the intestinal type of gastric cancer were reduced to 49.5% and 34.0 %." (PMID 26934326, 2016). "IKBKE, NF-κB p65 and phospho-NF-κB p65 proteins were highly enriched in MSC-like cells of gastric cancer tissues, and the latter two were correlated with the pathological progression of gastric cancer." (PMID 26934326, 2016).
pancreatic ductal adenocarcinoma (5 papers, 2020 to 2021). An infiltrating adenocarcinoma that arises from the epithelial cells of the pancreas. "Rajurkar et al40 showed that IKBKE promoted the reactivation of AKT postinhibition of mTOR in PDAC (pancreatic ductal adenocarcinoma) cells." (PMID 31733040, 2020). "This contrasts with observations in pancreatic ductal adenocarcinoma cell lines where IKBKE mediated phosphorylation of Akt and subsequent inhibition of GSK3β regulates the nuclear retention and stabilization of c-MYC without impacting on c-MYC mRNA." (PMID 32324216, 2020). "Cheng et al38 immunohistochemically evaluated IKBKE expression in 78 PDAC (pancreatic ductal adenocarcinoma) patients and found that IKBKE was overexpressed in 50 (64%) PDAC specimens." (PMID 31733040, 2020). "Similarly, IKBKE directly promotes nuclear localization and transcriptional activity of GLI1 in pancreatic ductal adenocarcinoma." (PMID 33637972, 2021). "Furthermore, IKBKE can regulate the stability and nuclear localization of c-MYC in pancreatic ductal carcinoma cell lines." (PMID 32324216, 2020).
Arthritis (4 papers, 2013 to 2024). Inflammation of a joint. "A novel functional heterozygous variant in IKBKE is described in a patient with a remittent fever and arthritis." (PMID 39524436, 2024). "IKBKE was recently reported to play a key role in MMP gene expression and subsequent joint destruction in arthritis, so we investigated whether IKBKE was a target mRNA of miR-155 in RA-FLS." (PMID 24151514, 2013).